FLT4 (fms related receptor tyrosine kinase 4)
Diseases named in the same sentence as FLT4 in open-access papers (continued):
Sharing a sentence is not in itself a finding about the gene and the disease.
Tetralogy of Fallot (10 papers, 2019 to 2025). A congenital cardiac malformation comprising pulmonary stenosis, overriding aorta, ventricular septum defect, and right ventricular hypertrophy. "These include an 8 kb deletion in FLT4 linked to tetralogy of Fallot and a 10 kb deletion in CHD7 associated with CHARGE syndrome caused by the insertion of an Alu element." (PMID 38339013, 2024). "A link has been reported between FLT4 loss-of-function mutations and the tetralogy of Fallot, and VEGF signaling seems to be a new mechanism contributing to the pathogenesis of the disease." (PMID 36496429, 2022). "The FLT4 mutations identified in patients with the tetralogy of Fallot are mainly missense or truncating variants in extracellular domains." (PMID 36496429, 2022). "Patients with the tetralogy of Fallot have inherited a variant of the FLT4 gene from an asymptomatic parent, indicating that the mutant allele has reduced penetrance." (PMID 36496429, 2022). "In a prior study, loss-of-function variants in the FLT4 gene were found in 2.3% of the recruited patients with the tetralogy of Fallot." (PMID 36496429, 2022). "Most FLT4 variants are associated with the tetralogy of Fallot; consequently, this CHD presents with a combination of defects such as ventricular septal defects, pulmonary valve stenosis, right ventricular hypertrophy, and the overriding aorta." (PMID 36496429, 2022). "The NOTCH1 and FLT4 genes are the genes most frequently implicated in the etiology of the tetralogy of Fallot, with their variants accounting for almost 7% of all cases." (PMID 36496429, 2022). "Moreover, many previous studies have suggested a close association between FLT4 gene immunoglobulin domain variations and the occurrence of congenital heart disease (Tetralogy of Fallot)." (PMID 41328432, 2025). "In that study, 22 FLT4 variants were reported in 21 patients with the tetralogy of Fallot." (PMID 36496429, 2022). "Recent studies have shown that FLT4 has an important genetic contribution to tetralogy of fallot (TOF)." (PMID 38581027, 2024). "Elsewhere, a frameshift deletion in the FLT4 gene in a patient with the tetralogy of Fallot was detected by WES." (PMID 36496429, 2022). "As anticipated, genes with harmful variants found in patients with tetralogy of Fallot-associated CHD, such as Kdr, Flt1, and Flt4, exhibit a high expression in E8.25–E8.5 endothelial cells, in line with the known functions of the encoded proteins in the VEGF pathway." (PMID 38339013, 2024). "Additionally, a deletion involving the FLT4 gene was described in a patient with the tetralogy of Fallot." (PMID 34946970, 2021). "Thus far, deleterious mutations in the FLT4 immunoglobulin domain were only reported in patients with the most common cyanotic congenital heart disease (Tetralogy of Fallot), who did not also appear to have MD." (PMID 34681005, 2021).
Insulin resistance (9 papers, 2016 to 2023). Increased resistance towards insulin, that is, diminished effectiveness of insulin in reducing blood glucose levels. "In addition, several energy metabolic processes, such as the PI3K-Akt pathway (EPHA2, FLT4, ITGA5, and LPAR6), cholesterol metabolism (APOE and CD36), and insulin resistance (FOLR1, CALM14, and PPP1R3A), were enriched in ApoE4 mice." (PMID 36720919, 2023).
thyroid cancer (9 papers, 2015 to 2023). "Out of 28 protein-coding, five genes; TERT, FLT4, DUSP6, USP10 and POMC have already been implicated in thyroid cancer." (PMID 32324757, 2020). "In addition, although FLT4 obtains a minor elevated expression in other cancer types than in thyroid cancers, the general FLT4 expression in all cancer types is weakly determined among all VEGF/VEGFR subunits." (PMID 35313079, 2022).
ischemic stroke (8 papers, 2014 to 2026). A stroke disorder caused by obstruction of blood flow to the brain, due to thrombotic (local blood clot formation) or embolic (due to a blood clot or other material traveling from another site) event. "FLT4 blockade can likely reduce the level of inflammation and reactivity of glial cells, since VEGFR-3 could be involved in the development of the inflammatory response of astrocytes in ischemic strokes." (PMID 33672819, 2021). "The involvement of FLT4 in the cascades initiating the maintenance of cell survival, neurogenesis, and angiogenesis, suggests that modulating the activity of VEGF receptors can be effective in the therapy of several neurodegenerative diseases and ischemic stroke." (PMID 33672819, 2021).
breast tumor (7 papers, 2013 to 2022). "Based on those phosphorylation patterns, a computational upstream kinase analysis predicted increased activity of PTKs that are known to contribute to invasive progression and metastasis of breast tumor, namely, FLT4, JAK1b, TRKB, and FLT1." (PMID 35847979, 2022). "FLT4 is a member of the VEGF receptor family, and expression in vessels surrounding breast tumors was correlated to lymph node positivity and poor clinical outcome." (PMID 23758962, 2013).
leukemia (7 papers, 2007 to 2025). A malignant (clonal) hematologic disorder, involving hematopoietic stem cells and characterized by the presence of primitive or atypical myeloid or lymphoid cells in the bone marrow and the blood. "Although there is a strong association between FLT4 and leukemia, they have been understudied, and consequently, the mechanism by which FLT4 may be implicated in leukemia and therapy resistance is unknown." (PMID 40316529, 2025). "We next examined the impact of FLT4 on leukemia progression in vivo by generating Reh cells expressing luciferase along with either FLT4 (vFLT4-Luc) or control (vEmpty-Luc) vectors." (PMID 40316529, 2025). "We next examined the impact of stimulating endogenous FLT4 on the signaling mechanisms found in leukemia." (PMID 40316529, 2025). "We next treated FLT4-overexpressing Reh cells with genotoxic drugs commonly used in the treatment of leukemia, Doxorubicin and Etoposide." (PMID 40316529, 2025). "Real-time (RT) PCR analysis was performed to quantify KDR and FLT4 expression in some ninety leukemia/lymphoma cell lines, human umbilical vein endothelial cells (HUVECs) and dermal microvascular endothelial cells (HDMECs)." (PMID 22251800, 2012). "In leukemia, the RTK FMS-Related Tyrosine Kinase 4 (FLT4) (also known as VEGFR3, Vascular Endothelial Growth Factor Receptor- 3) is deregulated and correlates with cancer progression." (PMID 40316529, 2025). "Our data obtained from primary endothelial cells and from leukemia/lymphoma cell lines show that KDR and FLT4 are epigenetically regulated genes." (PMID 22251800, 2012). "Expression of KDR and FLT4 was observed in cell lines from various leukemic entities, but not in lymphoma cell lines: 16% (10/62) of the leukemia cell lines expressed KDR, 42% (27/65) were FLT4 positive." (PMID 22251800, 2012).
preeclampsia (7 papers, 2012 to 2025). Preeclampsia is a hypertensive disorder of pregnancy that is characterized by new-onset hypertension with proteinuria presenting after 20 weeks of gestation, and depending on mild or severe forms may initially present with severe headache, visual disturbances, and hyperreflexia. "In white women, FLT1 rs722503, FLT4 rs307826, and VEGFC rs7664413 were significantly associated with preeclampsia." (PMID 36901702, 2023). "Another less known predictor of pregnancy complication is Flt-4 (also named as VEGFR3), a member of the VEGFR family and a relative to Flt-1 (VEGFR1), whose ratio with PlGF is widely used as a clinical predictor for impending preeclampsia and placenta related complications." (PMID 40698658, 2025).
glioma (6 papers, 2013 to 2021). A benign or malignant brain and spinal cord tumor that arises from glial cells (astrocytes, oligodendrocytes, ependymal cells). "No data are available for VEGFR-3 (flt4) which was demonstrated to be upregulated in VEGF-A driven angiogenesis, at least in gliomas in vitro and in vivo." (PMID 33528717, 2021). "FLT4 DEG is not expressed in endothelium of normal brain, in physiological adult tissues, but its mRNA was found only in high-grade gliomas and its expression has been correlated with tumor grade." (PMID 31231613, 2019).
head and neck cancer (6 papers, 2010 to 2023). A primary or metastatic malignant neoplasm affecting the head and neck. "The VEGFR3 (Flt4) mediate dissemination of several tumors and was found to be overexpressed in prostate, lung, colorectal, and head and neck cancers." (PMID 32752094, 2020).
lymphoma (6 papers, 2012 to 2024). A malignant (clonal) proliferation of B- lymphocytes or T- lymphocytes which involves the lymph nodes, bone marrow and/or extranodal sites. "To address this question, we validated eight plasma proteins (IL-17A, F5, FLT4, SFTPB, and GNPTG in lymphoma, TNFSF12, CCL3, and KIT in NSCLC) for response prediction and three plasma proteins (IL36G, SERPINC1, and LTA) for relapse monitoring." (PMID 38349411, 2024). "Five noninvasive biomarkers (FLT4, SFTPB, GNPTG, F5, and IL-17A) were further validated in an independent lymphoma cohort (n = 39), and another three noninvasive biomarkers (KIT, CCL3, and TNFSF1) were validated in NSCLC cohort (n = 76)." (PMID 38349411, 2024). "To identify specific predictive biomarkers, we selected five biomarkers (F5, FLT4, GNPTG, IL-17A, and SFTPB) that were differentially expressed between the R and NR patient groups in both lymphoma cohorts from the top 20% of significantly differentially expressed proteins (p < 0.05)." (PMID 38349411, 2024).
metastatic tumors (6 papers, 2012 to 2025). "Finally, in silico analysis of VEGFR3/FLT4/CD310 expression in samples from cancer patients revealed higher expression of VEGFR3/FLT4/CD310 in metastatic tumors, as well as an association between VEGFR3/FLT4/CD310 expression and poorer patient survival." (PMID 41459512, 2025). "FLT4 is identified as a marker of metastatic disease, and as a response marker for small molecule therapeutics that inhibit CRC metastasis." (PMID 25605009, 2015). "Moreover, VEGFR3 (FLT-4) promotes lymphangiogenesis, which is essential to metastatic tumors as well, through its binding to VEGF-C and VEGF-D." (PMID 39513922, 2024).
sarcoma (6 papers, 2010 to 2022). A usually aggressive malignant neoplasm of the soft tissue or bone. "The expression levels of sunitinib targeted-kinases were measured by transcriptome sequencing for PDGFRA/B, KIT, RET, FLT1(VEGFR1), KDR (VEGFR2), and FLT4(VEGFR3) for patient cohort with EMC and other sarcoma histologies." (PMID 28423517, 2017).
Kaposi's sarcoma (5 papers, 2007 to 2022). A malignant neoplasm characterized by a vascular proliferation which usually contains blunt endothelial cells. "Later studies discovered that VEGF-C’s primary receptor Flt4/VEGFR-3 is expressed in a variety of human malignancies, including lung, colorectal, prostate, and squamous cell carcinomas of the head and neck as well as Kaposi’s sarcoma." (PMID 25658842, 2015).
Cerebral ischemia (4 papers, 2014 to 2021). Restriction of arterial blood supply to the brain associated with insufficient oxygenation to support the metabolic requirements of the tissue. "Preservation of a functionally complete dynamic interaction between the components of neuron-glial networks allows us to consider FLT4 as a promising target for the development of methods of protection against cerebral ischemia and is of interest for future research." (PMID 33672819, 2021).
Chylothorax (4 papers, 2018 to 2025). The presence of chyle in the thoracic cavity. "Recently, variants of unknown significance (VUS) at the FLT4 locus were isolated in two primary isolated congenital chylothorax patients, thus highlighting the need for further characterization of VEGFR3 signaling in these disorders." (PMID 38201272, 2023).
congenital heart disease (4 papers, 2021 to 2025). A heart disease that is present at birth. "In addition, FLT4 (Fms Related Receptor Tyrosine Kinase 4) encodes the vascular endothelial growth factor receptor 3 (VEGFR-3) receptor and is described for its role in congenital heart disease." (PMID 36800380, 2023).
endometrial cancer (4 papers, 2003 to 2024). Primary or metastatic malignant neoplasm involving the endometrium (mucous membrane that lines the endometrial cavity). "STK11 and FLT4 genes were covered by CNVs in the relative of MPT21.2, who presented endometrial cancer." (PMID 39408606, 2024).
glaucoma (4 papers, 2017 to 2025). Increased pressure in the eyeball due to obstruction of the outflow of aqueous humor. "Among them, CPXM1 (OR: 0.53, 95% CI: 0.39 − 0.73, P < 0.001) and FLT4 (OR: 0.86, 95% CI: 0.78 − 0.95, P = 0.005) exhibited associations with glaucoma consistent with those of the corresponding proteins." (PMID 40635100, 2025). "Among actionable druggable genes, CPXM1 and FLT4 exhibited protective roles in glaucoma, supported by tier 1 evidence." (PMID 40635100, 2025). "FLT4, a candidate target gene with tier 1 evidence for association with glaucoma and for druggability, did not exhibit a significant association with IOP or RNFL." (PMID 40635100, 2025). "By using a comprehensive analysis pipeline, we identified five potential therapeutic targets for glaucoma: two tier 1 genes (CPXM1 and FLT4), one tier 2 gene (INSR), and two tier 3 genes (CPZ and PXDN)." (PMID 40635100, 2025).
glioblastoma (4 papers, 2014 to 2020). The most malignant astrocytic tumor (WHO grade IV). "In this study, we correlated glioblastoma locations with the expression of five mesenchymal genes (VEGFC and its receptor FLT4, HGF and its receptor MET, and CHI3L1) and five proneural genes (PROM1, NOTCH1, DLL3, PDGFRA, and BCAN)." (PMID 26637806, 2016). "Its main receptor, FLT4, was also strongly expressed in all glioblastomas of the present study, regardless of location." (PMID 26637806, 2016).
oral squamous cell carcinoma (4 papers, 2003 to 2023).
prostate tumors (4 papers, 2009 to 2023). "Integrative genomic analysis of primary prostate tumors and associated LNM demonstrated the enrichment of mutations in several genes including both well-established oncogenes and tumor suppressors and understudied genes such as EYA1, CSMD3, FLT4, NCOR2, and PCDH15." (PMID 38067373, 2023).
cholangiocarcinoma (3 papers, 2013 to 2023). A carcinoma that arises from the intrahepatic biliary tree (intrahepatic cholangiocarcinoma) or from the junction, or adjacent to the junction, of the right and left hepatic ducts (hilar cholangiocarcinoma). "We determined the gene expressions of FLT1, FLT4, HPSE, Hif1a, HB-EGF, PDGFA, PDGF-RA and EGFR in FFPE samples of patients with cholangiocarcinoma." (PMID 23704979, 2013).
cognitive decline (3 papers, 2021 to 2026). "Within the prefrontal cortex, higher expression of these four genes (VEGFB, FLT1, PGF, and FLT4) was associated with more rapid cognitive decline and higher pathology burden." (PMID 39641382, 2025). "When we expanded our analyses to brain tissues we observed that VEGFB, FLT1, PGF, and FLT4 all appear to contribute to the progression of AD pathology and cognitive decline." (PMID 39641382, 2025). "VEGF ligand and receptor genes, specifically genes relevant to FLT4 and FLT1 receptor signaling, are associated with cognition, longitudinal cognitive decline, and AD neuropathology." (PMID 31332262, 2021). "Prefrontal cortex expression of multiple VEGF genes, including ligand genes VEGFB and PGF and receptor genes FLT1 and FLT4, were associated with a more rapid rate of cognitive decline late in life, with VEGFB and FLT4 also associated with cognitive scores closest to death." (PMID 31332262, 2021).
Neuroendocrine Tumors (3 papers, 2018 to 2023). "Beyond PDAC, single nucleotide polymorphisms (SNPs) of FLT4 correlate with decreased progression-free survival of patients with gastroenteropancreatic neuroendocrine neoplasms." (PMID 33213062, 2020).
ventricular septal defect (3 papers, 2022 to 2024). The presence of a defect (opening) in the septum that separates the two ventricles of the heart. "In the current study, we detected a novel pathogenic variant in the FLT4 gene, which was associated with pulmonary atresia and ventricular septal defects in the first family." (PMID 36496429, 2022). "The detected variant in the FLT4 gene can change the arginine amino acid to a premature termination codon at position 82 in the VEGFR3 protein, denoting a feasible mechanism for the pathologies associated with pulmonary atresia and ventricular septal defects." (PMID 36496429, 2022).
viral infection (3 papers, 2020 to 2024). "Small interfering RNAs (siRNAs) were used to assess the impact of STC1 and FLT4 expression on viral infection and angiogenesis." (PMID 37740179, 2023).
brain infarction (2 papers, 2019 to 2021). Tissue necrosis in any area of the brain, including the cerebral hemispheres, the cerebellum, and the brain stem. "When simulating focal ischemia in rats, it was shown that blockade of FLT4 (VEGFR3) reduces activation of the lymphatic endothelium, reduces the level of activation of proinflammatory macrophages, and reduces the volume of cerebral infarction." (PMID 33672819, 2021).
colorectal tumor (2 papers, 2020 to 2025). "Although FLT4 was generally downregulated in primary colorectal tumors compared to normal tissue, it caught our attention that its expression is elevated in metastatic lesions and is associated with aggressive histological features such as mucinous tumors." (PMID 41459512, 2025).
cystic lung diseases (2 papers, 2012 to 2023). "Serum levels of vascular endothelial growth factor-D (VEGF-D), a ligand for the lymphatic growth-factor receptor VEGFR-3/Flt-4, are higher in most LAM patients than in healthy controls or in patients with other cystic lung diseases (OCLD)." (PMID 36817769, 2023). "Vascular endothelial growth factor-D (VEGF-D), a ligand for the lymphatic growth-factor receptor VEGFR-3/Flt-4, is elevated in serum of patients with LAM compared with healthy volunteers and patients with other cystic lung diseases." (PMID 22513045, 2012).
invasive carcinoma (2 papers, 2005 to 2020). A carcinoma that is not confined to the epithelium, and has spread to the surrounding stroma. "Comparing the expression of angiogenic markers between the groups of DCIS with (n=104) vs DCIS without (n=96) coexisting invasive carcinoma revealed that expression of VEGF-C, KDR, Flt-4, and ETAR was significantly more frequent in pure DCIS than in DCIS with an adjacent invasive carcinoma." (PMID 15841074, 2005). "With respect to our findings, it is conceivable that determination of VEGF-C, ETAR, KDR, and Flt-4 expression may facilitate discrimination of a more angiogenic subset within the group of non-high-grade DCIS without coexistent invasive carcinoma." (PMID 15841074, 2005).
medullary thyroid cancer (2 papers, 2023). "Newer drugs active against FLT4 or VEGFR3 have been recently licensed for use in medullary thyroid cancer and may be a promising therapy to consider in KS." (PMID 37740179, 2023).
Noonan syndrome (2 papers, 2021 to 2022). Noonan Syndrome (NS) is characterized by short stature, typical facial dysmorphism and congenital heart defects. "Examples of other genetic diagnoses included mosaic tetrasomy 8 (a variant of unknown significance on the Noonan syndrome panel), and FLT4 mutation." (PMID 33533966, 2021).